MAT2B (methionine adenosyltransferase 2 non-catalytic beta subunit)
Description:
Regulatory subunit of S-adenosylmethionine synthetase 2, an enzyme that catalyzes the formation of S-adenosylmethionine from methionine and ATP. Regulates MAT2A catalytic activity by changing its kinetic properties, increasing its affinity for L-methionine. Can bind NADP (in vitro).
Synonyms: TGR; Nbla02999; MATIIbeta; SDR23E1; MAT-II
Tractability: Small molecule: a structure with a bound ligand is known; it has a high-quality binding pocket. Antibody: the Human Protein Atlas places it where antibodies can reach. PROTAC: ubiquitination databases record sites on it; its protein half-life has been measured.
Gene: Protein-coding gene on chromosome 5 (163,503,114 to 163,519,558, forward strand). Ensembl gene ENSG00000038274.
Subcellular location (Human Protein Atlas): Plasma membrane
Pathways (Reactome):
Metabolism: Methylation
Metabolism of proteins: Ub-specific processing proteases
Gene Ontology:
Molecular function: enzyme binding; enzyme regulator activity; protein binding
Biological process: S-adenosylmethionine biosynthetic process
Cellular component: extracellular exosome; methionine adenosyltransferase complex; nucleus; cytosol
Genetic constraint (gnomAD): Loss-of-function variants: 11 observed, 27.14 expected, observed/expected ratio (o/e) 0.41, 90% interval 0.25 to 0.67. The upper end of that interval is the gene's LOEUF score, 0.67, which puts it in group 2 of 6, group 1 being the genes least tolerant of losing a copy. Missense variants: 264 observed, 327.69 expected, observed/expected ratio (o/e) 0.81, 90% interval 0.73 to 0.89. Synonymous variants: 121 observed, 112.89 expected, observed/expected ratio (o/e) 1.07, 90% interval 0.92 to 1.25.
Homologues: Orthologues: chimpanzee MAT2B (100% identical), guinea pig MAT2B (98% identical), rabbit MAT2B (97% identical), dog MAT2B (96% identical), macaque MAT2B (95% identical), rat Mat2b (95% identical), mouse Mat2b (94% identical), pig MAT2B (92% identical), tropical clawed frog mat2b (75% identical), zebrafish mat2b (66% identical).